SOX17 (SRY-box transcription factor 17)
Diseases named in the same sentence as SOX17 in open-access papers (continued):
Sharing a sentence is not in itself a finding about the gene and the disease.
endometrial cancer (16 papers, 2015 to 2026). Primary or metastatic malignant neoplasm involving the endometrium (mucous membrane that lines the endometrial cavity). "SOX17 has been classified as an oncogene in endometrial cancer for the presence of recurring missense mutations, antagonizing the canonical Wnt/β-catenin pathway." (PMID 33152990, 2020). "Endometrial tumors expressing higher SOX17 levels are associated with higher recurrence-free survival rates; conversely, progression of endometrial cancer may be promoted by low SOX17 expression through downregulation of MAML3 expression and Wnt signaling." (PMID 32039004, 2019). "Likewise, FOXA2 and SOX17 are primarily mutated in endometrial cancers, and ELMER identified network alterations specifically in this cancer type (UCEC)." (PMID 25994056, 2015). "Thus, nuclear accumulation of β-catenin is associated withnegative SOX17 in endometrial cancer (R = −0.392, P=0.001), suggesting that SOX17 could influence Wnt/β-catenin signaling." (PMID 27738313, 2016). "Another important gene in EC carcinogenesis is SOX17, which acts as a tumor suppressor gene, and its inactivation is important in endometrial cancer progression through EMT (epithelial–mesenchymal transition) regulation." (PMID 38542261, 2024). "This underscores SOX17 as a critical factor in the development and progression of endometrial cancer, potentially serving as a target for therapeutic intervention." (PMID 38981872, 2024). "To conclude, the findings imply that the enhanced expression of SOX17 considerably reduces the suppressive impact of ZBTB7A on malignant biological activities in endometrial cancer cells." (PMID 38981872, 2024). "SOX17 (SRY-box transcription factor 17) has been identified as a highly sensitive and specific marker for ovarian and endometrial carcinomas." (PMID 38981872, 2024). "The expressions of HOTAIR are positively related to SOX17, and both are significantly overexpressed in endometrial carcinoma." (PMID 38981872, 2024). "SOX17 has a suppressive effect and its overexpression promoted mesenchymal to epithelial transition, while SOX17 silencing induced EMT in endometrial cancer cell lines." (PMID 37511248, 2023). "Overexpression of miR-21-5p significantly inhibits SOX17 protein expression in endometrial cancer cell lines." (PMID 37511248, 2023). "Out of 120 endometrial cancer (EC) patients, we found that those with tumors expressing higher SOX17 (n=68) had longer recurrence-free survival (P=0.024), while higher MAML3 expression (n=76) was associated with shorter recurrence-free survival (P=0.022)." (PMID 27738313, 2016). "This indicates that HOTAIR may affect the biological characteristics of endometrial cancer by regulating the expression of SOX17." (PMID 38981872, 2024). "EMT promotion by miR-21-5p may be mediated by targeting SOX17 (SRY-box 17), and is correlated with poor survival in endometrial cancer patients." (PMID 38542261, 2024). "Furthermore, endometrial cancers with hyperbranched and hyperdense vascular tumors expressed more SOX17; SOX17 deletion suppressed angiogenesis in tumors and restored normalcy to tumor vasculature." (PMID 38136277, 2023). "However, SOX17 expression has been reported to increase the sensitivity to cisplatin in endometrial cancer (EC), which explains SOX17 having been proposed as a tumor suppressor." (PMID 33152990, 2020). "It has been postulated that SOX17 could act as a gene suppressor in the progression of endometrial cancer by directly regulating EMT and cancer cell proliferation." (PMID 33152990, 2020). "Our subsequent investigation focused on the impact of SOX17 overexpression on the restraining effect of ZBTB7A on malignant biological behaviors in HEC-1 A and KLE endometrial cancer cell lines." (PMID 38981872, 2024). "Our study has elucidated a crucial pathway in the pathogenesis of endometrial cancer (EC) involving the interaction between ELAVL1 and HOTAIR, which in turn influences the regulation of SOX17." (PMID 38981872, 2024).
endometrial cancer (continued). "Additionally, another study identified a a panel of fivegenes (ASRGL1, RHEX, SCGB2A1, SOX17, and STX18) as biomarkers for predicting lymph node metastasis in early-stage endometrial cancer patients." (PMID 39980551, 2025). "Quantitative PCR (qPCR) analysis revealed that the expression level of SOX17 in endometrial cancer tissues was significantly higher than in adjacent non-cancerous tissues." (PMID 38981872, 2024).
pulmonary arterial hypertension (15 papers, 2018 to 2025). "Rare genetic variation, primarily in genes associated with transforming growth factor-β family members, including BMPR2, but also in the transcription factor SOX17, is known to cause pulmonary arterial hypertension." (PMID 30527956, 2019). "The alleles associated withdisease were common, with a relatively modest effect size: for example, 59% of patientswith pulmonary arterial hypertension compared with 46% of controls were homozygous forthe risk allele at both SOX17 SNPs." (PMID 30527955, 2019). "The SOX17 locus had two independent signals associated with pulmonary arterial hypertension (rs13266183, 1·36 [1·25–1·48], p=1·69 × 10–12; and rs10103692)." (PMID 30527956, 2019). "Both in-silico and experimental analyses of the common variants upstream of the SOX17 gene suggest that they affect susceptibility to pulmonary arterial hypertension through regulation of SOX17 expression." (PMID 30527956, 2019). "SOX17 is associated with primary pulmonary hypertension (type 7) and its role in CTEPH may be plausible." (PMID 41300788, 2025). "is a risk factor for pulmonary arterial hypertension and dysregulation of SOX17 might be more common in pulmonary arterial hypertension than the occurrence of rare variants suggests." (PMID 30527956, 2019). "We investigated whether the HLA-DPA1/DPB1 and SOX17 variants affect clinical outcomes in pulmonary arterial hypertension, specifically all-cause mortality." (PMID 30527956, 2019). "SOX17 deficiency is linked to pulmonary arterial hypertension (PAH) risk via interactions with Hypoxia Inducible Factor 2 Alpha (HIF-2α)." (PMID 38474099, 2024). "This is the first study to report that common genetic variation at loci in an enhancer near SOX17 and in HLA-DPA1/DPB1 is associated with pulmonary arterial hypertension." (PMID 30527956, 2019). "Pulmonary arterial hypertension risk variants determined haplotype-specific enhancer activity, and CRISPR-mediated inhibition of the enhancer reduced SOX17 expression." (PMID 30527956, 2019). "Through a meta-analysis of 11 744 individuals, we have established loci at an enhancer upstream of SOX17 and at HLA-DPA1/DPB1 associated with pulmonary arterial hypertension disease risk." (PMID 30527956, 2019). "Studies in our lab aimed at testing this hypothesis by examining the effect of suppressed Sox17 expression on the expression of Runx1 in the lung and in progenitor cells of animals with pulmonary hypertension and patients with PAH are ongoing." (PMID 38028440, 2023). "SOX17 is a key endothelial regulator and its dysfunction in pulmonary arterial hypertension might be more common than suggested by the occurrence of rare pathogenic variants in heritable cases." (PMID 30527956, 2019). "In this study, it is shown that SOX17, serving as a key factor in maintaining endothelial function and vascular homeostasis, prevents endothelial dysfunction and pulmonary arterial remodeling through regulating exosomal miRNAs in an autocrine manner in pulmonary hypertension." (PMID 36919784, 2023). "Both the SOX17 and HLA-DPA1/DPB1 loci reached genome-wide significance in the discovery analyses; our cross-validation strategy confirmed that the same alleles were more frequent in pulmonary arterial hypertension than in other disease or population controls in both analyses." (PMID 30527956, 2019). "SOX17 enhancer knockout in mice reduced lung SOX17 expression, resulting in more severe pulmonary vascular leak and hypoxia or SU5416/hypoxia-induced pulmonary hypertension." (PMID 37066790, 2023). "Recent studies have unveiled that the dysregulation of SOX17 expression in IPAH patients significantly contributes to the disruption of endothelial functional homeostasis, thereby playing a pivotal role in the initiation and progression of pulmonary hypertension." (PMID 38586587, 2024).
colorectal cancer (14 papers, 2012 to 2025). A primary or metastatic malignant neoplasm that affects the colon or rectum. "As previously discussed, LGR5+ colorectal cancer stem cells upregulate the transcription factor SOX17, which suppresses expression of the stemness marker LGR5." (PMID 41346579, 2025). "In concordance with the SOX17 in colorectal cancer, in HCC, SOX17 is frequently methylated at its promoter region and occurs in approximately 82% of HCC samples." (PMID 35267473, 2022). "SOX17 was reported to be a candidate tumor suppressor gene that inhibits the canonical WNT/β-catenin signaling pathway in colorectal cancer and hepatocellular carcinoma." (PMID 22928040, 2012). "SOX17 exerts its action via the inhibition of the Wnt/β-catenin signaling pathway in cancer, and its methylation is related to the development of breast and colorectal cancers, and to PTC progression." (PMID 41463503, 2025). "As SOX17 associated with β-catenin has been shown to regulate the transcription of FOXA1 in endodermal and colorectal cancer cells, and β-catenin is reportedly influenced by JAM-A expression, we investigated whether JAM-A expressional alterations would change SOX17 expression." (PMID 33669586, 2021). "Forced expression of SOX17 repressed β-catenin signaling measured by pBAR in SW480 and HCT-116 colorectal cancer (CRC) cell lines, consistent with reported data." (PMID 28978154, 2017). "Quantitative methylation-specific PCR (qMSP) was used to evaluate methylation of four Wnt-antagonists, SFRP2, WIF-1, DKK3 and SOX17 in 18 normal colorectal mucosa samples, 9 colorectal cancer cell lines, 18 carcinomas, 44 nonpolypoid and 44 polypoid adenomas." (PMID 24350795, 2013).
cervical carcinoma (11 papers, 2014 to 2024). A carcinoma arising from either the exocervical squamous epithelium or the endocervical glandular epithelium. "SOX17 was the leading protein for skin NS cancer, stomach adenocarcinoma, endometrium endometrioid carcinoma, lung adenocarcinoma, and urinary tract NS cancer." (PMID 36672963, 2023). "In general, mRNA expression levels are lower in cervical cancer cells lines than in HaCaT cells, except for SOX17 and MYOD1 in SiHa cells, MGMT in C-33A cells and AJAP1, SOX17 and MYOD1 in HeLa cells." (PMID 34991696, 2022). "All these results indicated that SOX17 suppresses the tumor formation of cervical cancer cells in vivo by inhibiting the cell proliferative ability." (PMID 29970906, 2018). "Collectively, these results indicated that SOX17 suppressed the proliferation of cervical cancer cells through arrest at the cell transition from G0/G1 phase to the S phase." (PMID 29970906, 2018). "Collectively, all these results indicated that SOX17 suppressed the tumor formation of cervical cancer cells by inhibiting the cell proliferative ability in vivo and in vitro." (PMID 29970906, 2018). "The results showed that as the SOX17 expression increased, β-catenin expression decreased in the human cervical cancer tissues." (PMID 29970906, 2018). "SOX17 inhibited the proliferation and viability of cervical cancer cells in vitro as well as tumor formation in vivo." (PMID 29970906, 2018). "In the present study, the TOP/FOP flash luciferase reporter assay revealed that the Wnt/β-catenin signaling activity was attenuated by SOX17 in cervical cancer." (PMID 29970906, 2018). "In contrast, the expression levels of these proteins in SOX17- knockdown cervical cancer cells were significantly increased." (PMID 29970906, 2018). "Next, the recombinant β-catenin plasmid was transiently transfected in the SOX17-overexpressing cells and the results showed that the proliferation suppression and cell cycle arrest of cervical cancer cells by SOX17 were rescued." (PMID 29970906, 2018). "In this study, immunohistochemistry showed that the expression of SOX17 was high in the normal cervix, moderate in the high-grade squamous intraepithelial lesion, and low in the cervical cancer." (PMID 29970906, 2018). "The TOP/ FOP-Flash reporter assay and Western blotting showed SOX17 inhibited the activity of the Wnt/β-catenin signaling pathway in cervical cancer." (PMID 29970906, 2018). "All these data suggested that the activity of the Wnt/β-catenin signaling pathway is attenuated by SOX17 in cervical cancer cells." (PMID 29970906, 2018). "All these results demonstrated that the SOX17 protein suppresses tumor formation of cervical cancer cells in vivo." (PMID 29970906, 2018). "Consistent with the mRNA results, a significant decrease of β-catenin, cyclin D1, and c-Myc protein expression was found in the SOX17 overexpressing cervical cancer cells." (PMID 29970906, 2018). "All of these three molecules, β-catenin, cyclin D1 and c-Myc, were down-regulated by SOX17 in cervical cancer cells, but β-catenin is the upstream molecule of cyclin D1 and c-Myc in Wnt/β-catenin signaling pathway." (PMID 29970906, 2018). "The average SOX17 expression level was lower in cervical carcinoma tissues than in normal cervix tissues (0.67 ± 0.52 vs. 2.25 ± 1.54, p < 0.05)." (PMID 29970906, 2018). "Together, our data demonstrated that SOX17 restrained the proliferation and tumor formation by down-regulating the activity of the Wnt/β-catenin signaling pathway via trans-suppression of β-catenin in cervical cancer." (PMID 29970906, 2018). "It is revealed that SOX17 expression was found in cervical cancer cell lines." (PMID 29970906, 2018). "However, the biological function and molecular mechanism of SOX17 in the process of initiation and progression of cervical cancer remain obscure." (PMID 29970906, 2018).
cervical carcinoma (continued). "Therefore, a dual-luciferase reporter assay was performed to identify if SOX17 directly bind the promoter of β-catenin in cervical cancer cells." (PMID 29970906, 2018). "The MSP was performed and showed different levels of methylation of SOX17 in cervical cancer cells." (PMID 29970906, 2018). "Whether SOX17 participates in the process of initiation and progression of cervical cancer and how it contributes to the cervical carcinogenesis remain obscure." (PMID 29970906, 2018). "The results showed that SOX17 expression was significantly reduced in cervical cancer (p < 0.001)." (PMID 29970906, 2018). "Thus, the recombinant β-catenin plasmid was transiently transfected into the SOX17-overexpressing cells to detect if the proliferation suppression of cervical cancer cells by SOX17 could be rescued." (PMID 29970906, 2018). "Furthermore, the molecular mechanisms of SOX17 in cervical carcinoma initiation and progression are largely unknown." (PMID 29970906, 2018). "Taken together, our findings suggested that SOX17 inhibited the tumor formation, proliferation and activity of the Wnt/β-catenin signaling pathway by directly binding to the region between the −1756 and −1473 nucleotides in the β-catenin promoter in cervical cancer cells." (PMID 29970906, 2018). "The aim was to investigate the diagnostic value provided by methylation biomarkers of six tumor suppressor genes (ASTN1, DLX1, ITGA4, RXFP3, SOX17 and ZNF671) for cervical precancerous lesions and cervical cancer." (PMID 36803573, 2023). "In previous studies we have shown that hypermethylation of CpG islands in proximity to the genes DLX1, ITGA4, RXFP3, SOX17, and ZNF671 correlated with the presence of cervical precancerous lesions and cervical cancer." (PMID 30509219, 2018). "The expression status of SOX17 was first evaluated in normal human cervix (NC), high-grade squamous intraepithelial lesion (HSIL) and cervical cancer (CC) samples by immunohistochemistry (IHC)." (PMID 29970906, 2018). "A methylation signature comprising the 5′ regions of the genes DLX1, ITGA4, RXFP3, SOX17 and ZNF671 specific for CIN3 and cervical cancer (termed CIN3+) was identified and validated." (PMID 24647315, 2014). "In cervical cancer a DNA hypermethylation marker panel consisting of the six marker regions ASTN1, DLX1, ITGA4, RXFP3, SOX17, and ZNF671 may be a useful tool for triaging HPV-positive women." (PMID 30509219, 2018). "DNA isolated from 49 tissue samples with no histological evidence for CIN (normal), from 43 samples diagnosed as CIN3 and from 54 cervical cancer tissues was bisulfite-treated and used in qMSP experiments for the five marker regions DLX1, ITGA4, RXFP3, SOX17, and ZNF671." (PMID 24647315, 2014). "In the present study, IHC and western blot analysis revealed low expression of SOX17 expression in cervical cancer and the MSP assays showed high methylation of SOX17 promoter in cervical cancer cell lines, indicating that SOX17 might suppress the progression of cervical cancer." (PMID 29970906, 2018). "Moreover, the negative correlation of SOX17 and β-catenin expression was observed in the clinical cervical cancer specimen." (PMID 29970906, 2018).
colon carcinoma (9 papers, 2009 to 2024). "According to PubMed literature review, Snail, SOX17, HNF3β, c-FOS, and RORα-1 have been confirmed to be associated with colon cancer." (PMID 34337040, 2021). "We next focused directly on β-catenin, since it has been reported as necessary for SOX17 transcription of FOXA1 and associated with regulating the transcription factor ZEB-1 by the tight junction protein Claudin-1 in colon cancer cells." (PMID 33669586, 2021). "SOX17 is epigenetically inactivated by promoter methylation in many cancers including colon cancer and regarded as a canonical Wnt antagonist." (PMID 25868860, 2015). "Only 5 of the 14 transcription factors (Snail, SOX17, HNF3 β, c-FOS, and RORα-1) are involved in the occurrence and development of colon cancer, consulting the literature through the PubMed database." (PMID 34337040, 2021). "Dietary administration of black raspberries resulted in demethylation of WIF1, SOX17, and GKI in in vivo colon cancer models." (PMID 33375383, 2020). "In studies of other authors, dietary application of black raspberries (BRB) rich in numerous flavonoids such as anthocyanidins led to demethylation of tumor-suppressor gene promoters, including WIF1, SOX17, and GKI in precancerous colon cancer in vivo." (PMID 32204409, 2020). "Furthermore, qRT-PCR analysis for Wnt target genes (including cMyc, Ascl2, Axin2, CD44, CD1, Sox17, Wif1 and Tiam1) did not identify any significant differences between the colonic tumours isolated from both cohorts of mice." (PMID 25881306, 2015).
embryonal carcinoma (9 papers, 2010 to 2026). A non-seminomatous malignant germ cell tumor characterized by the presence of large germ cells with abundant cytoplasm resembling epithelial cells, geographic necrosis, high mitotic activity, and pseudoglandular and pseudopapillary structures formation. "The oncogenic transformation of hPGCs into pluripotent embryonal carcinoma (EC) cells and germ cell tumours entails the loss of SOX17 and the gain of SOX2 function." (PMID 35411086, 2022). "SOX17, a marker of seminomatous identity, was consistently reduced, while SOX2, which is associated with pluripotency and embryonal carcinoma-like features, was upregulated or unchanged." (PMID 40649953, 2025). "In SE, SOX17 stimulates genes that inhibit differentiation but allows SE to be transformed into embryonal carcinoma (EC)." (PMID 36835562, 2023). "This study suggests that activation of SOX17 together with stimulation of WNT, TGF‐beta / Activin and FGF signaling drives embryonal carcinomas into the yolk‐sac tumor lineage." (PMID 40025812, 2025).